RARRES1 (retinoic acid receptor responder 1)
Description:
Inhibitor of the cytoplasmic carboxypeptidase AGBL2, may regulate the alpha-tubulin tyrosination cycle.
Synonyms: PERG-1; TIG1; LXNL
Tractability: Antibody: UniProt places it where antibodies can reach, with high confidence; UniProt predicts a signal peptide or a membrane-spanning region; its Gene Ontology location is reachable by antibodies, with medium confidence.
Gene: Protein-coding gene on chromosome 3 (158,696,892 to 158,732,798, reverse strand). Ensembl gene ENSG00000118849.
Subcellular location: Membrane; Secreted
Subcellular location (Human Protein Atlas): Golgi apparatus; Endoplasmic reticulum
Gene Ontology:
Molecular function: protein binding; metalloendopeptidase inhibitor activity
Biological process: negative regulation of cell population proliferation
Cellular component: extracellular exosome; extracellular region; membrane
Genetic constraint (gnomAD): Loss-of-function variants: 31 observed, 28.42 expected, observed/expected ratio (o/e) 1.09, 90% interval 0.82 to 1.47. The upper end of that interval is the gene's LOEUF score, 1.47, which puts it in group 6 of 6, group 1 being the genes least tolerant of losing a copy. Missense variants: 316 observed, 307.2 expected, observed/expected ratio (o/e) 1.03, 90% interval 0.94 to 1.13. Synonymous variants: 130 observed, 112.67 expected, observed/expected ratio (o/e) 1.15, 90% interval 1 to 1.34.
Homologues: Orthologues: chimpanzee RARRES1 (98% identical), macaque RARRES1 (93% identical), rabbit RARRES1 (72% identical), pig RARRES1 (70% identical), mouse Rarres1 (69% identical), rat Rarres1 (69% identical), dog RARRES1 (63% identical), guinea pig RARRES1 (52% identical), tropical clawed frog rarres1 (29% identical). Paralogues in human: LXN (23% identical).
Diseases named in the same sentence as RARRES1 in open-access papers:
RARRES1 is named in the same sentence as 80 diseases in open-access papers, as found by Europe PMC text mining. Sharing a sentence is not in itself a finding about the gene and the disease. The quoted sentences say what the papers report.
breast cancer (17 papers, 2012 to 2025). A primary or metastatic malignant neoplasm involving the breast. "In support of this notion, our group recently discovered that hypermethylation at the RARRES1 promoter flanking sequences can be induced by an exposure to breast cancer-associated fibroblasts." (PMID 22615834, 2012). "Subsequently, downregulated RARRES1 triggered various malignant properties and was associated with advanced neoplastic states in various cancer types and in breast carcinomas (current report)." (PMID 22615834, 2012). "However, breast cancer associated tumor suppressor genes such as RARRES1, SPARC, SOCS3, and LIF were also up-regulated in T47D cells." (PMID 25776849, 2015). "In this study, RARRES1 was found to be highly expressed in epithelial cells (CSCs) and fibroblasts, and studies have revealed the possibility that RARRES1 can be used as a carcinoma-associated fibroblast (CAF) marker gene in breast cancer and may lead to chemotherapy resistance." (PMID 36424614, 2022). "Boxplot analyses revealed that MELK, BIRC5, and CEACAM6 were significantly overexpressed in HR+/HER2– breast cancer tissues compared to normal breast tissues in the TCGA cohort, whereas RARRES1 expression was markedly reduced in tumor tissues (p < 0.001)." (PMID 40936892, 2025). "Kaplan–Meier survival analysis indicated that high RARRES1 expression was also a protective factor for overall survival in patients with luminal breast cancer." (PMID 38533207, 2024). "RARRES1 has a tumor suppressor role in numerous human cancers, including breast cancer, prostate cancer, osteosarcoma, choriocarcinoma, and kidney renal clear cell carcinoma." (PMID 38388961, 2024). "There is additional evidence that the propensity for fatty acid metabolism alters in breast cancer subtypes with differential RARRES1 expression." (PMID 36110217, 2022). "As expected, EPB41L4A-AS2 inhibited breast cancer cell proliferation, migration and invasion and induced cell apoptosis partly via the upregulation of RARRES1 expression." (PMID 30764831, 2019). "There is also evidence of changes in fatty acid metabolism preference in different subtypes of breast cancer, in which RARRES1 is differentially expressed." (PMID 30557378, 2018). "High levels of RARRES1 in clinical breast cancer samples are correlated with a more aggressive phenotype (by Ki67 positivity and overall grade) and poor patient outcome." (PMID 28423353, 2017). "For example, methylation of RARRES1 correlates with RARβ promoter methylation in prostate cancer and treatment of colon and breast carcinoma cells with AZA induced a demethylation of the RARβ promoter region and a restoration of RARβ expression." (PMID 29169400, 2017). "These correlations between ALDH1A3 and RARRES1 suggests that expression of RARRES1 in breast cancer is not only controlled by methylation in the promoter region, but also by ALDH1A3 via its production of RA." (PMID 27286452, 2016). "In this study, we focus on RARRES1 as a paradigm to determine if protein function and gene expression regulation in breast cancer is dictated by subtype." (PMID 27286452, 2016). "RARRES1 is a commonly silenced hypermethylated locus in many cancer types including prostate cancer, hepatocellular carcinoma, and breast cancer." (PMID 27286452, 2016). "In this study, we focus on retinoic acid receptor responder 1 (RARRES1) as a paradigm to determine if breast cancer subtype dictates protein function and gene expression regulation." (PMID 27286452, 2016). "This pattern is consistent with the specific hypomethylation of RARRES1 in basal-like breast cancer." (PMID 27286452, 2016). "To investigate if RARRES1 represents a gene that is differentially expressed in the molecular subtypes of breast cancer, we obtained data from the 2012 TCGA breast cancer data set using the cBioportal interface." (PMID 27286452, 2016).
breast cancer (continued). "Although generally described as a putative tumor suppressor gene, a recent report indicated a pro-tumorigenic role for RARRES1 in a rare form of breast cancer, inflammatory breast cancer." (PMID 27286452, 2016). "We then investigated the possible mechanisms for the differential expression of RARRES1 across the breast cancer subtypes." (PMID 27286452, 2016). "These are in contrast to a functional study in the rare inflammatory subtype of breast cancer (representing less than 5% of all breast cancers), where RARRES1 was oncogenic." (PMID 27286452, 2016). "Patient tumor dataset analysis and gene expression studies of a 26 cell-line panel, representing the five breast cancer subtypes, demonstrate that RARRES1 expression is greatest in basal-like TNBCs." (PMID 27286452, 2016). "Future treatment regimen by abrogating this trigger and thus blocking region P methylation followed by sustaining RARRES1 expression could potentially improve disease prognosis via hampering metastasis, the common cause of death in a wide range of human carcinomas including breast cancer." (PMID 22615834, 2012). "We first compared methylation occurring at the sequences (−664∼+420) flanking the RARRES1 promoter in primary breast carcinomas to that in adjacent benign tissues." (PMID 22615834, 2012). "Importantly, the top 4 genes induced by OSM in CAF-173 (SERPINB4, THBS1, RARRES1, and TNC) are associated with decreased overall survival in breast cancer patients." (PMID 35192545, 2022). "Thus, EPB41L4A-AS2 functions as a tumor suppressor at least in part via the upregulation of RARRES1 expression in breast cancer." (PMID 30764831, 2019). "In breast cancer cells RARRES1 was reported to interfere with beta-Catenin and AGBL2 function." (PMID 29169400, 2017). "Furthermore, given these prior reports of both tumor suppressing and oncogenic effects of RARRES1, we considered if RARRES1 expression in a breast cancer subtype influences its function." (PMID 27286452, 2016). "Importantly, the specific expression and hypomethylation of RARRES1 in basal-like breast cancer adds RARRES1 to a list of genes which are differentially regulated and expressed in breast cancer subtypes." (PMID 27286452, 2016). "RARRES1 is one example of a gene that fits this paradigm and may suggest that a specific subtype of breast cancer (i.e. basal-like breast cancers) could be treated with RA." (PMID 27286452, 2016). "Furthermore, gene expression studies, Illumina HumanMethylation450 arrays, and chromatin immunoprecipitation demonstrate that expression of RARRES1 is retained in basal-like breast cancers due to hypomethylation of the promoter." (PMID 27286452, 2016). "We also identified significant variability of RARRES1 expression within the basal-like cell lines, which may reflect the heterogeneity known to exist within this breast cancer subtype." (PMID 27286452, 2016). "Only recently has AGLB2 been identified as the TCP that regulates the tubulin tyrosination cycle by interacting with retinoic acid receptor responder 1 (RARRES1), a carboxypeptidase inhibitor that is suppressed in aggressive prostate and breast cancer cells with a mesenchymal phenotype." (PMID 24028602, 2013). "Taken together, our data supported RARRES1 to be a tumor suppressor gene in breast cancer and its downregulation, by DNA methylation, CTCF binding, or by histone remodeling, might favor dissemination and survival of breast carcinoma." (PMID 22615834, 2012). "We assessed the levels of methylation at sequences flanking RARRES1 promoter in 18 pairs of breast tumor cores plus adjacent benign tissues as well as in breast cancer cell lines and have discovered methylation at two regions can exert strikingly distinct epigenetic outcomes." (PMID 22615834, 2012). "Notably, RARRES1 expression level was significantly different between subtypes of breast cancer." (PMID 38533207, 2024).
breast cancer (continued). "Therefore, the increased expression of RARRES1 in basal-like tumors is not due to overall greater hypomethylation of basal-like cancers, and suggests an alternative hypothesis – the specific hypomethylation of RARRES1 in basal-like breast cancer." (PMID 27286452, 2016). "Though metastasis property correlated with a gain of tumor-initiating cells enriched in the ALDEFLUOR-positive subfraction, RARRES1-restoration didn’t render a loss of breast cancer-initiating cells (data not shown), excluding the likelihood that RARRES1 regulates this activity." (PMID 22615834, 2012). "Specifically, RARRES1 level was significantly higher in TNBC than in Luminal or HER2-positive breast cancer, and it was also significantly higher in HER2-positive breast cancer than in luminal breast cancer." (PMID 38533207, 2024). "In addition, THBS1, RARRES1, and TNC levels correlate with OSMR expression in breast cancer clinical samples." (PMID 35192545, 2022). "However, the tumor suppressive effect of RARRES1 on breast carcinomas has not been proven so far, but began to be illustrated in current report." (PMID 22615834, 2012). "During the progression of breast carcinomas, perhaps, the non-malignant stage would sustain region D at the unmethylated state and thus facilitate the binding of CTCF to R4 region of RARRES1 promoter by which methylation at region P can be prevented." (PMID 22615834, 2012). "We did not observe any relevant correlation between RARRES1 expression and RAR/RXR expression, suggesting that expression of these nuclear receptors was not dictating expression of RARRES1 in breast cancer." (PMID 27286452, 2016).
prostate carcinoma (14 papers, 2014 to 2025). A carcinoma that arises from epithelial cells of the prostate gland. "In prostate cancer an association between RARRES1 hypermethylation and worse clinical outcome was reported." (PMID 29169400, 2017). "In prostate cancer, epigenetic silencing of RARRES1 was shown to be associated with poor prognosis." (PMID 38533207, 2024). "Prior research has established a correlation between the transcriptional silencing of RARRES1 in esophageal, gastric, endometrial, and prostate cancers and epigenetic inactivation resulting from promoter hypermethylation." (PMID 38898266, 2024). "Previous studies have shown that RARRES1 activates autophagy to inhibit tumor progression in prostate cancer and cervical cell carcinoma." (PMID 38898266, 2024). "We showed in prostate cancer cells that RARRES1 is able to induce autophagy, decrease mechanistic target of rapamycin (mTOR) and increase Sirtuin 1 (SIRT1), two important regulators of energy homeostasis." (PMID 30557378, 2018). "RARRES1 is silenced in colorectal cancer, prostate cancer, nasopharyngeal cancer, Wilms tumor and leukemia." (PMID 30557378, 2018). "During nutrient deprivation, fatty acid degradation is necessary and fatty acid synthesis, specifically DNL, is increased in metastasis and certain cancers like prostate cancer, consistent with the decrease of RARRES1 expression in prostate cancer." (PMID 30557378, 2018). "We also show that RARRES1 expression correlates with that of fatty acid metabolism genes in breast, colorectal and prostate cancers." (PMID 30557378, 2018). "Retinoic acid receptor responder (RARRES1) is a putative tumor suppressor gene that suppress invasion and colony-forming ability of prostate cancer cells." (PMID 26973595, 2016). "Additionally, hypermethylation of the RARRES1 promoter leads to reduced expression in liver cancer, prostate cancer, breast cancer, and colorectal cancer." (PMID 38898266, 2024). "RARRES1 acted as an invasion suppressor in prostate cancer and triple-negative breast cancer." (PMID 36353618, 2022). "RARRES1 may induce autophagy in prostate cancer and cervical cancer cells." (PMID 33587010, 2021). "Co-localisation of RARRES1 protein with the ER marker protein disulfide isomerase in LNCaP and PC3 prostate cancer cell lines proved that RARRES1 localises to the ER, whereas RARRES1 was absent from the nucleus." (PMID 32307444, 2020). "Several are known biomarkers for diagnosis and prognosis of prostate cancer (APC, GSTP1, KIT, PYCARD, PGDGRB, RARB, RARRES1, and TIMP1) and some though not biomarkers, were found to be dysregulated in the disease (CDKN1B, MMP7, and MMP9)." (PMID 24626295, 2014).
colorectal cancer (5 papers, 2012 to 2024). A primary or metastatic malignant neoplasm that affects the colon or rectum. "Both in vitro and in vivo experiments consistently demonstrated that increased expression of RARRES1 suppressed the proliferation of A375 cells, which aligns with the observations made in a prior study conducted on colorectal cancer cells." (PMID 38898266, 2024). "Common pathways identified in the analysis of genes co-expressed with RARRES1 in breast, prostate, and colorectal cancers." (PMID 30557378, 2018). "It has been demonstrated that the down-regulation of RARRES1 is related to tumor growth of colorectal cancer and nasopharyngeal carcinoma." (PMID 23951052, 2013). "In addition, aberrant RARRES1 expression can induce activation of M1 microphage in kidney renal clear cell carcinoma and inhibit cells proliferation in colorectal cancer respectively." (PMID 38898266, 2024). "Downregulation of RARRES1 was suggested to be related to stage D progression of colorectal cancer." (PMID 23049694, 2012).
glioblastoma (4 papers, 2021 to 2024). The most malignant astrocytic tumor (WHO grade IV). "And RARRES1 contributes to the regulation of dendritic cells and serves as a novel immune-related biomarker for glioblastoma." (PMID 36950684, 2023). "A recent study confirmed that RARRES1 contributed to the regulation of dendritic cells and acted as a novel immune-related biomarker for glioblastoma." (PMID 33587010, 2021). "RARRES1 is enriched in glioblastoma multiforme (GBM), particularly WHO grade-IV cases; and high expression of RARRES1 is a predictor of poor prognosis, indicating that it may participate in GBM pathogenesis, and is a potential therapeutic target in this context." (PMID 38388961, 2024).
glomerular disease (4 papers, 2024 to 2025). "In the context of kidney diseases, RA can promote apoptosis of podocytes and their loss by suppressing the expression of RARRES1, which has recently been described as a risk factor for the progression of glomerular diseases." (PMID 38374141, 2024). "This appears to be the case for retinoic acid receptor responder protein-1 (RARRES1), a podocyte-enriched transmembrane protein whose expression is increased in kidney biopsies of patients with glomerular diseases." (PMID 39529801, 2024). "Notably, retinoic acid receptor responder 1 (Rarres1) is detectably expressed in glomerular and peritubular capillary endothelial cells in IgA nephropathy and related glomerulopathies." (PMID 41357229, 2025). "Additionally, RARRES1 fragments may potentially leak into the renal tubular lumen, influencing renal tubular cells and serving as messengers in intercellular crosstalk during the development of glomerulopathy and chronic kidney disease." (PMID 38374141, 2024).
inflammatory breast carcinoma (4 papers, 2016 to 2025). An advanced, invasive breast adenocarcinoma characterized by the presence of distinct changes in the overlying skin. "In contrast, RARRES1 acts as an anti-apoptotic factor in inflammatory breast cancer, where it facilitates cell survival and promotes proliferation and migration." (PMID 41178994, 2025). "However, several studies suggested that high RARRES1 expression is significantly correlated with poorer clinical outcomes in patients with clear cell renal cell carcinoma and inflammatory breast cancers." (PMID 38533207, 2024). "Our finding that RARRES1 has tumor suppressive effects in TNBC regardless of subtype, differs from previous findings which suggested that RARRES1 is oncogenic in inflammatory breast cancer." (PMID 27286452, 2016).
melanoma (4 papers, 2011 to 2024). A malignant, usually aggressive tumor composed of atypical, neoplastic melanocytes. "According to the results of the enrichment analysis, it was found that RARRES1 is strongly correlated with the migration and invasion of melanoma." (PMID 38898266, 2024). "We found that RARRES1 was significantly reduced in SKCM patients of T4 stage, pathological stage II, age over 60, with melanoma ulcer, higher Clark level, higher Breslow thickness and without radiotherapy, indicating decreased RARRES1 expression was associated with poor clinical features of SKCM." (PMID 38898266, 2024). "This may be attributed to the lower expression levels of RARRES1 in gastric cancer and melanoma." (PMID 38533207, 2024). "We identified four genes, PPP1R3C, ENC1, RARRES1 and TP53INP1 that were not previously known to be silenced by DNA methylation in melanoma." (PMID 22028813, 2011).
breast tumors (3 papers, 2012 to 2017). "Moreover, the roles RARRES1 plays in breast neoplasm remain largely undiscovered to date." (PMID 22615834, 2012). "Next, to determine the mechanism for the subtype-specific hypomethylation or silencing of the RARRES1 tumor suppressor, we analyzed HM450 data available from the TCGA data portal for 220 patient breast tumors." (PMID 27286452, 2016). "It is noteworthy to mention that methylated D plus unmethylated P regions somewhat recapitulated the physiological mosaic at the RARRES1 promoter observed in primary breast tumors and is in a strong agreement with a lack of silencing effect." (PMID 22615834, 2012).